GPX3 (glutathione peroxidase 3)
Diseases named in the same sentence as GPX3 in open-access papers (continued):
Sharing a sentence is not in itself a finding about the gene and the disease.
Stroke (10 papers, 2012 to 2024). Sudden impairment of blood flow to a part of the brain due to occlusion or rupture of an artery to the brain. "Deficiency of GPX3 in humans has been associated with stroke and ischemic heart disease, and Gpx3-knock-out mice have a prothrombotic state and vascular dysfunction due to the accumulation of reactive oxygen species (ROS)." (PMID 35042540, 2022). "GPX3 polymorphisms have been associated with increased risk of stroke, while rs8177409 has been associated with increased cardiovascular risk." (PMID 34545296, 2021). "GPx-3 activity having already been shown to be implicated in arterial thrombosis and stroke in clinical studies." (PMID 23923054, 2013). "GPx3 deficiency is associated with risk of stroke and embolism." (PMID 39765894, 2024). "Moreover, a promoter haplotype of GPx-3 with reduced function is associated with increased stroke risk, indicating that normal GPx-3 function is crucial for preventing stroke, potentially by suppressing platelet-dependent thrombosis." (PMID 36439687, 2022). "GPx3 deficiency also has a role in promoting thrombotic disease and enhancing injury in stroke." (PMID 34579115, 2021). "Some of the stroke subtype-specific proteins (FBLN1, F2, SERPINF2, CBP2, FCN3, GPX3, IKG, and GSN) were also affected by the CBS deficiency." (PMID 31242583, 2019). "Other studies have shown that GPx3 expression is upregulated in hypoxia, suggesting it may protect against ROS-induced damage during ischemia-reperfusion injury, such as in stroke." (PMID 34579115, 2021). "Furthermore, low GPx3 has been related to CV disease (CVD) risk factors such as renal failure, increased inflammation, and increased tendency of platelet-dependent thrombo-embolism with an increased tendency of stroke." (PMID 39765894, 2024). "In this nested, case-control, prospective study, the serum GPx3 activity was inversely and linearly correlated with CVD mortality, including coronary heart disease, other atherosclerotic disease and stroke." (PMID 22719980, 2012).
type 2 diabetes (10 papers, 2015 to 2025). "In this study, we found that female patients with type 2 diabetes at high risk of progressive cardio-renal disease have a relatively greater increase in central obesity and a surprisingly elevated activity of GPx-3 compared with men." (PMID 31817851, 2019). "Our data suggest that women with type 2 diabetes at increased risk of renal and cardiovascular disease have higher GPx-3 activity, which is abrogated by increasing central fat deposits compared to men." (PMID 31817851, 2019). "It will be instructive to determine whether weight loss sustains GPx-3 activity and/or conversely stimulating GPx-3 activity reduces oxidative stress and cardio-renal risk in men and women with type 2 diabetes." (PMID 31817851, 2019). "There are few other clear human data on serum GPX3 levels in type 1 diabetes, while there are several reports on type 2 diabetes with other comorbidities, including suggestions that the serum/plasma levels are related to oxidative stress and dependent on the extent of disease progression." (PMID 37537394, 2023). "Antioxidant treatment in patients with type 2 diabetes and early CKD stages can derepress renal blood flow and improve the eGFR, directly correlated with GPX3 activity." (PMID 38927092, 2024). "However, studies have shown that GPX3 mRNA expression is significantly lower in the adipose tissue of type 2 diabetes (T2D) patients than in individuals with normal glucose metabolism." (PMID 38927092, 2024). "Thus, a decrease in GPx3 activity is associated with progression of mean carotid intima-media thickness (IMT) and the presence of carotid plaque, which confirms the relationship between GPx3 activity and the pathogenesis of carotid atherosclerosis in patients with type 2 diabetes." (PMID 35625904, 2022).
coronary artery disease (9 papers, 2012 to 2025). "Recently, low levels of GPx-3 activity has been associated with platelet-dependent thrombosis, increased risk for arterial stroke in young adults and children and coronary artery disease." (PMID 23923054, 2013). "Moreover, when other antioxidant-related gene polymorphisms (SOD2, SOD3, PON1, and GSTT1) are present, GPX3 rs3828599 is more strongly associated with the incidence of hypertension and is positively associated with coronary artery disease and with the severity of coronary atherosclerosis." (PMID 41152890, 2025). "Univariate analysis showed that age, smoking, previous coronary heart disease, carotid plaque, and level of mean CIMT and hypersensitive C‐reactive protein were significantly associated with decreasing tertile of GPx3." (PMID 32862561, 2020). "Recently, it was found that GPx activity and GPx-3 mRNA were upregulated in patients with acute coronary syndromes compared to patients with stable coronary artery disease and healthy controls." (PMID 31817851, 2019). "The participants with lower activity of GPx3 was more likely to be older (p = .009) and to have higher mean CIMT (p = .004) and hs‐CRP (p = .012) levels, as well as to have the history of smoking (p = .025), previous coronary heart disease (p = .042), and carotid plaque (p = .049)." (PMID 32862561, 2020).
Sepsis (9 papers, 2013 to 2024). Sepsis is defined as life-threatening organ dysfunction caused by a dysregulated host response to infection. "Considering the acute oxidative stress observed in sepsis patients, it is interesting to observe that Gpx3 bioactivity is inversely associated with the severity of sepsis and associated mortality." (PMID 34349874, 2021). "Selenium and GPx-3 deficiency have been associated with sepsis." (PMID 36459524, 2022). "The biological activity of GPx-3 has been reported to be negatively correlated with mortality and disease severity in patients with sepsis." (PMID 39438952, 2024). "Extensive experiments are needed to verify the clinical application of SERPINA1 and GPX‐3 in sepsis and uncover the mechanisms of them as a biomarker for sepsis." (PMID 34825737, 2022). "Sepsis‐related decline of GPX‐3 protein concentration resulted in the decrease in GPX‐3 bioactivity." (PMID 34825737, 2022). "Almost all patients with sepsis admitted to ICUs have low plasma selenium levels and GPx-3 activity, which correlates inversely with severity of sepsis and mortality rate." (PMID 23372722, 2013). "Thus, the expression of GPX3-related antioxidant pathways is down-regulated during sepsis, thereby exacerbating oxidative stress and possibly contributing to further exacerbation of SIM." (PMID 39438952, 2024). "Moreover, it has been observed that Glutathione peroxidase 3 (GSH-Px-3) activity is decreased in patients with sepsis, due to a lower expression of GSH-Px-3, as these patients usually have lower levels of selenium, which limits the synthesis of this enzyme." (PMID 36551843, 2022). "This suggests that cogon grass root may ameliorate sepsis by increasing the platelet level, GPx3 activity, hepatocyte count, and cardiomyocyte count, as well as by reducing the lymphocyte count, monocyte count, TNF-α expression, and FABP4 level." (PMID 38559341, 2021). "Thus, although understanding of the mechanisms of regulation of Gpx3 expression and its pathophysiological role in sepsis is limited, Gpx3 could be a promising biomarker for assessing oxidative stress." (PMID 34349874, 2021).
atrial fibrillation (7 papers, 2019 to 2025). A disorder characterized by an electrocardiographic finding of a supraventricular arrhythmia characterized by the replacement of consistent P waves by rapid oscillations or fibrillatory waves that vary in size, shape and timing and are accompanied by an irregular ventricular response. "Reduced circulating levels of GPX3 was significantly associated with an increased risk of cardiovascular events in patients with atrial fibrillation." (PMID 38727290, 2024). "In patients with atrial fibrillation, a decline of Gpx3 was associated with an increased risk of cardiovascular events." (PMID 35997993, 2023). "It had been reported that the age-related decline of GPX3 may increase the risk of cardiovascular events in patients with atrial fibrillation." (PMID 37633909, 2023). "Similarly, circulating levels of the extracellular GPX isoform (GPX3) were inversely related to the risk of cardiovascular events in patients with atrial fibrillation in a prospective cohort study with 909 patients." (PMID 31404994, 2019). "Notably, an age‐related decline in GPX3 expression may heighten susceptibility to cardiovascular events in patients with atrial fibrillation." (PMID 39900557, 2025). "Postoperative atrial fibrillation (POAF), a common complication following CABG surgery, has been linked to increased GPX3 activity, indicating that GPX3 may be developed as a biomarker for predicting POAF." (PMID 38927092, 2024). "Recently, the serum GPx3 activity has been measured in participants with atrial fibrillation and the results showed that decreasing GPx3 activity may be a predictor of fatal and nonfatal cardiovascular complications." (PMID 32862561, 2020).
cervical cancer (7 papers, 2017 to 2024). A primary or metastatic malignant neoplasm involving the cervix. "It has been found that the methylation of GPX3, a member of the GPX family of tumor-suppressor genes, increases the risk of breast, live, and cervical cancer substantially." (PMID 36081670, 2022). "We can still identify some genes related to cervical cancer progression from the samples of the two patients after treatment, including ATF3, GPX3, IL10, IL6, RAD51AP1, MGMT, WWOX." (PMID 37914994, 2023).
clear cell renal cell carcinoma (7 papers, 2015 to 2025). "Hypoxia was shown to be a strong inducer of GPX3 promoter activity in the renal clear cell carcinoma cell line Caki-2, and GPx3 expression is an important component of the antioxidant defense mechanisms that protect rats from acute hypobaric hypoxia exposure." (PMID 32781581, 2020). "Thus, GPX3 and DIO1 expression may serve a potential diagnostic indicator in KIRC, representing a potential mechanism of sufficient selenium status in the human body protecting against renal clear cell carcinoma genesis." (PMID 32316597, 2020).
leukemia (7 papers, 2016 to 2022). A malignant (clonal) hematologic disorder, involving hematopoietic stem cells and characterized by the presence of primitive or atypical myeloid or lymphoid cells in the bone marrow and the blood. "Our study concludes that GPX3 methylation in bone marrow is associated with adverse prognosis and leukemia transformation in MDS." (PMID 27891827, 2017). "In summary, GPX3 methylation in bone marrow is associated with adverse prognosis and leukemia transformation in MDS." (PMID 27891827, 2017). "One research found that individuals with myelodysplastic syndrome, leukemia transformation, or acute myeloid leukemia who had high levels of GPX3 methylation in their bone marrow had a poor prognosis." (PMID 35069731, 2022). "In leukemia with a high frequency of stem cells, ROS levels were low and ROS-scavenging GPX3 levels were high compared to leukemia with a low frequency of stem cells." (PMID 35155201, 2021). "Altogether these data reinforce the identification of a key role of the BM microenvironment in the control of the GPx3-ROS-p38MAPK axis in leukemia and of the oxidative metabolism of leukemic blasts." (PMID 33202543, 2020). "Herault and colleagues found that this gene is crucial for the competitiveness of leukemia stem cells (LSCs) and the self-renewal of hematopoietic stem cells (HSCs) and GPX3 levels were correlated with the self-renewal activity of LSCs." (PMID 33369453, 2020). "Modulation of the GPx3/H2O2/p38 MAPK pathway could be a extended in clinical trials for leukemia patients for finding novel methods in targeting LSCs in the microenviroment." (PMID 33369453, 2020). "Intracellular reactive oxygen species (ROS) are involved in the regulation of the biology of leukemia-initiating cells, where the antioxidant enzyme GPx-3 could be involved as a determinant of cellular self-renewal." (PMID 33202543, 2020). "Epigenetic inactivation of GPX3 has been identified in various cancers including leukemia." (PMID 27891827, 2017). "Moreover, function role of GPX3 has also been investigated in leukemia." (PMID 27891827, 2017).
atherosclerosis (6 papers, 2012 to 2025). A disease characterized by the build-up of fatty material and calcium deposition in the arterial wall resulting in partial or complete occlusion of the arterial lumen. "Among many factors that contribute to the risk of atherosclerosis in plasma, great emphasis is placed on GPX-3, a basic extracellular peroxidase, that plays a significant role in the modulation of oxidative stress." (PMID 39859026, 2024). "Moreover, a reduction in GPX3 levels has been implicated in the pathogenesis of atherosclerosis and thrombosis." (PMID 39900557, 2025). "We therefore assume that low GPx3 activity may reflect an activation status of inflammation, which might cause endothelial dysfunction and arterial stiffness, and contribute to atherosclerosis." (PMID 32862561, 2020). "In contrast, serum GPx3 activity was significantly and inversely correlated to mean carotid intima-media thickness and carotid plaque (indexes of atherosclerosis) in a cohort of patients with T2D, suggesting that both excess and deficiency of GPx3 may cause deleterious effects." (PMID 35740085, 2022). "Since oxidized LDL is thought to initiate atherosclerosis and the serum glutathione peroxidase (GPx3) reduces oxidized lipids, we investigated whether high GPx3 activity reduces cardiovascular disease (CVD) mortality." (PMID 22719980, 2012). "Thus, GPx3 may be a determinant mediator in diseases which may impair endothelial function and result in atherosclerosis." (PMID 32862561, 2020). "Experimental evidences showed that GPx‐3 can catabolize hydrogen peroxide under circumstances of normal metabolism or oxidative insult, therefore preserving the vascular endothelium‐derived vasorelaxation and anti‐atherosclerosis." (PMID 32862561, 2020).
Barrett esophagus (6 papers, 2014 to 2023). Esophageal lesion lined with columnar metaplastic epithelium which is flat or villiform. "GPX3 can catalyze the reduction of peroxides and protect cells against oxidative damage and its hypermethylation has been found in esophageal adenocarcinoma." (PMID 31962291, 2020). "GPX3 promoter methylation has been shown in ESCC and esophageal glandular lesions, including Barrett’s esophagus and EA." (PMID 33292587, 2020).
endometrial adenocarcinoma (6 papers, 2009 to 2024). "In a previous microarray study performed by our group, Gpx3 was identified as a potential biomarker for rat endometrial adenocarcinoma (EAC), since the expression was highly downregulated in rat EAC tumors." (PMID 21106063, 2010). "Based on the content of these classifiers, Gpx3 and Bgn are the best individual marker genes and should be investigated for their potential value in diagnosis of human endometrial adenocarcinoma." (PMID 19426485, 2009). "The present results agree with other studies that showed downregulation of GPX3 in endometrial adenocarcinoma and early invasive breast carcinoma regardless of patients' clinical and pathological criteria." (PMID 24790704, 2014).
asthma (5 papers, 2014 to 2024). "In contrast, in other conditions of redox stress and inflammation, GPx3 expression has been shown to increase, and high GPx3 levels in extracellular fluids are associated with chronic inflammatory diseases such as asthma and metabolic syndrome." (PMID 32781581, 2020). "That PA27 has high level of transcripts encoding the antioxidant Gpx3 and proenkephalin (an attenuator of substance P that promotes asthma via the PI3K/Akt/Nfκb pathway in bronchial epithelium) speaks to a potential protective effect mediated by this T cell in lung." (PMID 39141734, 2024). "Additionally, genetic studies have identified GPX3 rs2070593 as a protective locus against asthma development, with two allelic mutations in GPX3 rs2070593 preventing the development of asthma." (PMID 38927092, 2024). "Microarray expression analyses and bronchial biopsy evaluations conducted in asthma patients and healthy controls have revealed the downregulation of GPX3 expression in asthma patients." (PMID 38927092, 2024).
bladder cancer (5 papers, 2012 to 2023). "Namely, analysis of data in TCGA and GTEx databases revealed that GPX3 gene expression, associated with several tumor types, was higher in normal bladder tissue than in bladder carcinoma tissue." (PMID 37629712, 2023). "High-grade bladder cancer is associated with low urinary GPx3 levels." (PMID 34926458, 2021). "Recently, downregulation of GPX3 by promoter hypermethylation has been reported in multiple human cancers, such as prostate, gastric, esophageal, cervical, and bladder cancer, suggesting that GPX3 serves as a tumor suppressor in these cancers." (PMID 25970749, 2015). "Moreover, GPX3 level was significantly lower in urine of patients with bladder carcinoma than in controls." (PMID 37629712, 2023). "GPX3 mRNA is expressed in a wide range of normal human tissues, however, downregulation of GPX3 has been found in multiple human cancers, such as prostate, gastric, esophageal, cervical, and bladder cancer, suggesting its importance in human tumorigenesis." (PMID 25970749, 2015).
colitis (5 papers, 2018 to 2025). Inflammation of the colon. "In a murine model of azoxymethane (AOM)/DSS-induced colitis, Gpx3-deficient mice developed a greater number of tumors and with advanced staging and local invasion, along with enhanced inflammation and increased DNA damage." (PMID 41300456, 2025). "As for the other isoforms with antioxidant role in the gut, the loss of GPx3 was linked to inducing severe colitis, while plasma GPx3 showed potent tumor suppressor role in colitis-associated carcinoma through abrogation of ROS." (PMID 30258848, 2018). "The mechanism by which GPX3 restricts the development of colitis can be divided into two types, affecting the M2 macrophage subpopulation and promoting proliferation." (PMID 37741901, 2023). "GPX3 is a tumor suppressor gene that takes an important part in balancing reactive oxygen species (ROS) in colitis, thereby inhibiting cancer progression." (PMID 33968130, 2021). "When GPX3-/- mice are exposed to azoxymethane/dextran sodium sulfate (AOM/DSS), loss of GPx3 accelerates the development of colonic high-grade dysplasia and increases expression of inflammatory markers in this colitis inflammatory carcinogenesis model." (PMID 32781581, 2020). "Therefore, both GPX3 and SEPP1 may influence intratumoral macrophage composition and function, thereby serving as tumor suppressors in colitis-associated cancer models." (PMID 41300456, 2025).
esophageal squamous cell carcinoma (5 papers, 2015 to 2023). Esophageal squamous cell carcinoma (ESCC) is a type of esophageal carcinoma (EC) that can affect any part of the esophagus, but is usually located in the upper or middle third. "In esophageal squamous cell carcinoma, GPx3 inhibits tumor migration and invasion through the FAK/AKT pathway." (PMID 34926458, 2021). "GPx3 can also suppress the expression of matrix metalloproteinase 9 (MMP-9) by deactivating the focal adhesion kinase (FAK)-AKT pathway, leading to decreased invasiveness of esophageal squamous cell carcinoma cells." (PMID 32781581, 2020).